CCDC144NL (CCDC144A N-terminal like (pseudogene))
Synonyms: MGC87631
Gene: Transcribed unprocessed pseudogene on chromosome 17 (20,893,392 to 20,896,020, reverse strand). Ensembl gene ENSG00000205212.
Diseases named in the same sentence as CCDC144NL in open-access papers:
CCDC144NL is named in the same sentence as 10 diseases in open-access papers, as found by Europe PMC text mining. Sharing a sentence is not in itself a finding about the gene and the disease. The quoted sentences say what the papers report.
proliferative diabetic retinopathy (1 paper, 2024). Advanced retinopathy due to diabetes mellitus characterized by the formation of new vessels in the retina. "Additionally, CCDC144NL was one of the genes selected for a combinatorial molecular signature as a potential biomarker for early detection of proliferative diabetic retinopathy." (PMID 38904047, 2024).
cancer (2 papers, 2017 to 2021). A tumor composed of atypical neoplastic, often pleomorphic cells that invade other tissues. "Variations in the CCDC144NL gene were associated with poor prognosis and may facilitate cancer metastatic progression." (PMID 34573430, 2021). "Those CNC variations associated with poor outcome (MUC5B, ZXDB, PLIN4, CCDC144NL, CNTNAP3B, and CCDC180) may probably facilitate cancer initiation and progression, and may be a new clue to study cancer metastasis and evolution." (PMID 29262625, 2017).
CCDC144NL also shares sentences with these, for which no sentence is quoted: bladder urothelial carcinoma (1 paper); breast carcinoma (1); diabetes (1); gastric cancer (1); hepatocellular carcinoma (1); laryngeal carcinoma (1); lung carcinoma (1); oesophageal cancer (1).